SLC15A2 (solute carrier family 15 member 2)
Description:
Proton-coupled amino-acid transporter that transports oligopeptides of 2 to 4 amino acids with a preference for dipeptides. Transports neutral and anionic dipeptides with a proton to peptide stoichiometry of 2:1 or 3:1 (By similarity). In kidney, involved in the absorption of circulating di- and tripeptides from the glomerular filtrate. Can also transport beta-lactam antibiotics, such as the aminocephalosporin cefadroxil, and other antiviral and anticancer drugs. Transports the dipeptide-like aminopeptidase inhibitor bestatin (By similarity). Also able to transport carnosine. Involved in innate immunity by promoting the detection of microbial pathogens by NOD-like receptors (NLRs) (By similarity). Mediates transport of bacterial peptidoglycans across the plasma membrane or, in macrophages, the phagosome membrane: catalyzes the transport of certain bacterial peptidoglycans, such as muramyl dipeptide (MDP), the NOD2 ligand.
Synonyms: PEPT2
Tractability: Small molecule: it belongs to a druggable protein family. Antibody: UniProt places it where antibodies can reach, with high confidence; its Gene Ontology location is reachable by antibodies, with high confidence; UniProt predicts a signal peptide or a membrane-spanning region. PROTAC: a small molecule that binds it is known.
Target class: SLC superfamily of solute carriers; SLC15 family of peptide transporters; Electrochemical transporter; Transporter
Gene: Protein-coding gene on chromosome 3 (121,894,391 to 121,944,188, forward strand). Ensembl gene ENSG00000163406.
Subcellular location: Apical cell membrane; Cytoplasmic vesicle, phagosome membrane; Cell membrane
Gene Ontology:
Molecular function: dipeptide transmembrane transporter activity; peptide:proton symporter activity; protein binding; tripeptide transmembrane transporter activity; oligopeptide transmembrane transporter activity; transmembrane transporter activity
Biological process: antibacterial innate immune response; dipeptide import across plasma membrane; dipeptide transport; peptidoglycan transport; regulation of nucleotide-binding domain, leucine rich repeat containing receptor signaling pathway; renal absorption; transport across blood-brain barrier; tripeptide import across plasma membrane; xenobiotic detoxification by transmembrane export across the plasma membrane; xenobiotic transport; oligopeptide transport; proton transmembrane transport; transmembrane transport
Cellular component: extracellular exosome; phagocytic vesicle membrane; plasma membrane; apical plasma membrane; membrane
Genetic constraint (gnomAD): Loss-of-function variants: 63 observed, 67.37 expected, observed/expected ratio (o/e) 0.94, 90% interval 0.76 to 1.15. The upper end of that interval is the gene's LOEUF score, 1.15, which puts it in group 5 of 6, group 1 being the genes least tolerant of losing a copy. Missense variants: 725 observed, 746.8 expected, observed/expected ratio (o/e) 0.97, 90% interval 0.91 to 1.03. Synonymous variants: 265 observed, 266.53 expected, observed/expected ratio (o/e) 0.99, 90% interval 0.9 to 1.1.
Homologues: Orthologues: chimpanzee SLC15A2 (99% identical), macaque SLC15A2 (98% identical), rabbit SLC15A2 (89% identical), dog SLC15A2 (88% identical), pig SLC15A2 (88% identical), mouse Slc15a2 (83% identical), rat Slc15a2 (82% identical), guinea pig SLC15A2 (78% identical), tropical clawed frog slc15a2 (56% identical), zebrafish slc15a2 (53% identical). Paralogues in human: SLC15A1 (46% identical), SLC15A4 (18% identical), SLC15A3 (17% identical), SLC15A5 (15% identical).
Diseases named in the same sentence as SLC15A2 in open-access papers:
SLC15A2 is named in the same sentence as 48 diseases in open-access papers, as found by Europe PMC text mining. Sharing a sentence is not in itself a finding about the gene and the disease. The quoted sentences say what the papers report.
glioma (7 papers, 2020 to 2025). A benign or malignant brain and spinal cord tumor that arises from glial cells (astrocytes, oligodendrocytes, ependymal cells). "The greatest difference in mRNA expression was found in SLC15A2 with a 2.66-fold higher mRNA expression in WHO grade II (11.01 ± 1.07) compared to WHO grade IV gliomas (9.60 ± 1.17; p < 0.0005)." (PMID 32722247, 2020). "SLC15A2, a peptide transporter, is widely expressed in the lungs, kidneys, brain, and eye and is highly expressed in human glioma cells, where it mediates carnosine uptake, although its role in cell proliferation requires further exploration." (PMID 34977043, 2021). "In this sense, we recently observed significant differences in the mRNA expression in 8 of 11 analyzed genes (HMBS, UROD, FECH, PPOX, SLC15A2, ALAD, UROS, and ABCB6) involved in the heme biosynthesis between WHO grade II and IV gliomas." (PMID 33562253, 2021). "Significant differences in mRNA expression included increases of HMBS, UROD, FECH and PPOX as well as decreases of SLC15A2, ALAD, UROS and ABCB6 in WHO IV gliomas." (PMID 32722247, 2020).
hepatocellular carcinoma (5 papers, 2015 to 2021). A malignant tumor that arises from hepatocytes. "Interestingly, patients with specific mutations in SLC15A2 (encoding Pept2) have a longer progression-free survival against hepatocellular carcinoma when treated with sorafenib." (PMID 34881291, 2021). "For hepatocellular carcinoma (HCC), whole-genome sequencing analysis revealed that single-nucleotide variations (rs2257212) of SLC15A2 demonstrated better progression-free survival and regulated the sorafenib treatment response." (PMID 34168674, 2021).
lung carcinoma (3 papers, 2021 to 2023). "In lung cancer, SLC15A4, the analog of SLC15A2, was associated with survival and cell division regulation." (PMID 34977043, 2021). "SLC15A2 has been widely studied and is expressed at relatively low levels in lung carcinoma." (PMID 34168674, 2021). "Our results showed that SLC15A2 and SLC15A3 RNA expression levels were decreased in lung cancer tissues compared with normal tissues by Oncomine pan-cancer analysis." (PMID 34168674, 2021).
porphyria (3 papers, 2020 to 2023). Porphyria is a group of diseases in which substances called porphyrins build up, negatively affecting the skin or nervous system. "Interestingly, a variant of SLC15A2 predicts the severity of porphyria-associated kidney disease." (PMID 32584883, 2020).
chronic myelogenous leukemia (2 papers, 2018 to 2024). "Chronic myeloid leukemia (CML) stem cells were found to be maintained by dipeptides accumulated via upregulated expression of Slc15A2 dipeptide transporters." (PMID 30191140, 2018).
prostate carcinoma (2 papers, 2020 to 2021). A carcinoma that arises from epithelial cells of the prostate gland. "SLC15A2 encodes peptide transporter 2 (PEPT2) that was over-expressed in prostate cancer cell lines, however, expression of SLC15A2 at the mRNA level was found to be lower in prostate cancer tissue than benign prostatic hyperplasia (BPH) tissue." (PMID 32584883, 2020). "Regarding prostate cancer, PEPT1, as well as PEPT2 (SLC15A2), were found to be expressed in the prostate cancer cell lines PC-3 and LNCaP, respectively, and further controlled the cellular uptake of Gly-Sar and L-histidine, indicating their role in the tumor metabolism process." (PMID 34168674, 2021).
leukaemia (1 paper, 2015). "Intriguingly, prior to IM therapy, SLC15A2 mRNA levels were indeed higher in BM leukaemia cells of nine CML patients than in the BM haematopoietic cells of nine healthy individuals." (PMID 26289811, 2015).
lung adenocarcinoma (1 paper, 2021). A carcinoma that arises from the lung and is characterized by the presence of malignant glandular epithelial cells. "We found that there was little difference between lung adenocarcinoma and squamous cell carcinoma in SLC15A1, SLC15A2 and SLC15A3." (PMID 34168674, 2021). "Briefly, all genes in SLC15A family could be used as clinical outcome prediction biomarkers in NSCLS, while SLC15A2 and SLC15A4 are with favorable prognostic value in lung adenocarcinoma." (PMID 34168674, 2021). "Only SLC15A2 and SLC15A4 were suitable to predict the clinical outcome of lung adenocarcinoma." (PMID 34168674, 2021). "Although all family members exhibited an association with the clinical outcomes of patients with NSCLC, we found that none of them could be used for squamous cell carcinoma of the lung and that SLC15A2 and SLC15A4 could serve as biomarkers for lung adenocarcinoma." (PMID 34168674, 2021). "Our results clearly showed that only SLC15A2 and SLC15A4 could be used as clinical outcome prediction biomarkers for overall survival rate in lung adenocarcinoma with HR = 0.57 (0.45–0.72); log rank P-value = 2.5e-06 and HR = 0.4 (0.38–0.62); log rank P-value = 8.7e-09, respectively." (PMID 34168674, 2021).
lymphoma (1 paper, 2021). A malignant (clonal) proliferation of B- lymphocytes or T- lymphocytes which involves the lymph nodes, bone marrow and/or extranodal sites. "SLC15A2 also displayed a pan-cancer decreased pattern, especially in kidney, lung and lymphoma." (PMID 34168674, 2021).
renal fibrosis (1 paper, 2026). A final common manifestation of a wide variety of chronic kidney diseases characterized by glomerulosclerosis and tubulointerstitial fibrosis. "Collectively, these findings identify a quercetin-SLC15A2 axis through which the SKR inhibits EMT and alleviates renal fibrosis in DKD, providing a mechanistic basis for its clinical application and nominating SLC15A2 as a potential therapeutic target." (PMID 41977470, 2026).
systemic lupus erythematosus (1 paper, 2025). An autoimmune multi-organ disease typically associated with vasculopathy and autoantibody production. "Among the 127 likely pathogenic terms associated with those 68 SLCs (Fig. EV2C), we found systemic lupus erythematosus (SLE) associated with SLC15A2, SLC15A4, and SLC17A3." (PMID 40355757, 2025).
tumor (10 papers, 2011 to 2026). "This integrative exposome-genome analysis highlights dioxin-related transcriptomic dysregulation in LUAD and identifies SLC15A2 as a potential tumor suppressor and biomarker for precision stratification." (PMID 42189270, 2026). "Functional experiments confirmed that SLC15A2 overexpression suppressed LUAD cell proliferation and invasion, supporting a tumor-suppressive role." (PMID 42189270, 2026).
cancer (8 papers, 2015 to 2026). A tumor composed of atypical neoplastic, often pleomorphic cells that invade other tissues. "Pan-cancer analyses revealed significant dysregulation of SLC15A2, with lower expression in LUAD associated with poorer survival." (PMID 42189270, 2026). "All of the four SLC transporters showed associations only with increased OS rates in cancers, including 1) SLC15A2 (LUAD), SLC22A1 (LIHC), SLC22A2 (KIRC, KIRP), and SLC22A6 (KIRC)." (PMID 33202946, 2020). "SLC15A2 had a controversial expression pattern with SLC15A3 across the pan-cancer study, where SLC15A1 showed a down-regulated expression in most of solid cancers and SLC15A4 displayed an up-regulated pattern." (PMID 34168674, 2021). "SLC15A3 and SLC15A4 were different from SLC15A1 and SLC15A2, with increased patterns in pan-cancer compared with normal tissue." (PMID 34168674, 2021). "As SLC15A2 RNA-seq expression is ultra-low and intensively studied in cancer, we aimed to reveal more molecular functions of SLC15A4." (PMID 34168674, 2021). "According to our selection standard for those cancers with unique analysis, the studies included were SLC15A1 (7:24), SLC15A2 (13:48), SLC15A3 (27:13), and SLC15A4 (12:3)." (PMID 34168674, 2021). "Finally, even if genetic variability for PEPT1 and PEPT2 is rather low, there is a recent report investigating the PEPT2 genetic variant rs2257212 (SLC15A2 c.1048C>T, p.L350F) as a potential predictor of actinomycin D (act D) pharmacokinetics in pediatric cancer patients." (PMID 32806706, 2020). "Unlike SLC15A1 and SLC15A2, which are frequently studied in the cancer field, the roles of SLC15A3 and SLC15A4 in cancer are quite opaque." (PMID 34168674, 2021).
SLC15A2 also shares sentences with these, for which no sentence is quoted: kidney damage (3 papers); chronic kidney disease (2); diabetes (2); infection (2); kidney disease (2); pancreas tumor (2); atherosclerosis (1); benign prostatic hyperplasia (1); breast carcinoma (1); Crohn disease (1); dengue (1); diabetic kidney disease (1); Dubin-Johnson syndrome (1); Encephalopathy (1); glioblastoma (1); Hartnup disorder (1); hearing loss (1); heart failure (1); Hyperglycemia (1); hyperuricemia (1); imbalance (1); Obesity (1); oesophageal cancer (1); pancreatic cancer (1); polyneuropathy (1); pulmonary disease (1); pulmonary fibrosis (1); renal dysfunction (1); renal failure (1); sarcoma (1).
A further 5 diseases each share a sentence with SLC15A2 in 1 paper.